PAX8 (paired box 8)
Diseases named in the same sentence as PAX8 in open-access papers (continued):
Sharing a sentence is not in itself a finding about the gene and the disease.
ovarian carcinoma (continued). "Comprehensive genomic screens furthermore indicate an additional oncogenic role for PAX8 in renal and ovarian cancers." (PMID 33903593, 2021). "Subsequently, the role of ADSCs in advancing ovarian cancer development was explored, and the effect of PAX8 was also identified during this process." (PMID 33830648, 2021). "Our results confirm that ADSCs are necessary for TAZ protein stability and also promote TAZ transcription in the ovarian cancer through PAX8 up‐regulation." (PMID 33830648, 2021). "We found that the expression of PAX8, a marker of ovarian cancer, was higher in cisplatin-resistant ovarian cancer organoids than those with cisplatin sensitivity, but FBP1 was opposite." (PMID 34363022, 2021). "The bioluminescence images captured in vivo manifested that the proliferation and the PAX8 expression level in ovarian cancers increased in the ADMSC‐treated group, and the effect of ADSCs in promoting tumours was weakened through inhibiting PAX8." (PMID 33830648, 2021). "Then, the PAX8 expressions in ovarian cancer tissues and fallopian tubes tissue (normal) were compared, revealing a much higher level of PAX8 expression in ovarian cancer tissues." (PMID 33830648, 2021). "The staining results reveal a significant increase of PAX8 expression in the tissues of ovarian and endometrial cancer compared to the adjacent tissues, especially in serous tumours such as ovarian cancer and clear cell carcinoma." (PMID 33830648, 2021). "The results confirmed that compared with cells cultured in the normal medium, PAX8 was expressed at much higher levels in the two ovarian cancer cell lines treated with ADSC CM." (PMID 33830648, 2021). "This study aims to study the effect of PAX8 induced by ADSCs on ovarian cancer's growth and invasion through stabilizing TAZ." (PMID 33830648, 2021). "In order to study PAX8, we inserted a BioID-HA cassette into the endogenous PAX8 locus in IGROV-1 ovarian cancer cells using CRISPR-Cas9." (PMID 33903593, 2021). "Collectively, our data indicate that PAX8 and MECOM splice variants, including the ovarian cancer-specific PRDM3, reside in the same protein complex." (PMID 33903593, 2021). "Via IPA, the analyses identified PAX8 (Paired Box 8) as a potential common target of miR-432-5p, miR-127-3p, and miR-138-5p involved in ovarian cancer pathophysiology." (PMID 33737539, 2021). "Of note, PAX8 was found to be amplified in 16% of primary ovarian cancers while shRNA mediated silencing of PAX8 lead to apoptosis in cell lines harboring either PAX8 amplification or overexpression." (PMID 33669749, 2021). "In ovarian cancers, PAX8 has been reported to interact with the Hippo pathway effectors YAP and TEAD10." (PMID 33903593, 2021). "It was found that PAX8 was up‐regulated significantly in ovarian cancer cells treated with ADSC, accompanied by the hippo signalling pathway activation." (PMID 33830648, 2021). "PAX8 is also being used to differentiate primary ovarian carcinoma from metastatic carcinomas and as an additional way to confirm the diagnosis of cervical carcinomas." (PMID 34540435, 2021). "A series of xenograft experiments were performed to investigate the effect of PAX8 on the capability of ADSCs to advance ovarian cancer development in vivo." (PMID 33830648, 2021). "Large-scale functional genomic screens have identified critical TFs necessary for lineage-specific proliferation of cancer cells and, in the case of ovarian cancer, indicated PAX8 as a key driver of cancer cell proliferation." (PMID 33903593, 2021). "In comparison with the ovarian cancer cells cultured in the common growth medium, those cultured in the medium supplemented with ADSCs showed a significant increase of the PAX8 level." (PMID 33830648, 2021). "For instance, MDS1 and EVI1 complex loci (MECOM) interact with PAX8 and drive oncogenic functions in ovarian cancer." (PMID 34722520, 2021).
ovarian carcinoma (continued). "These different responses to PAX8 or MECOM knockdown is suggestive of a weaker contribution of MECOM to ovarian cancer growth, possibly due to its cofactor activity." (PMID 33903593, 2021). "We and others have previously reported cell cycle and metabolism gene expression programs controlled by PAX8 in the kidney or ovarian cancer cells by binding to enhancer elements." (PMID 33903593, 2021). "High throughput shRNA screen performed by Project Achilles identified PAX8 as one of the potential oncogenes from 11,194 genes, which is necessary for the proliferation and survival of ovarian cancer cell lines (n = 25)." (PMID 33488950, 2020). "Silencing of PAX8 resulted in decreased migration, invasion, anchorage-independent growth, tumor formation, induced G1 arrest, and apoptosis in ovarian cancer cells." (PMID 33488950, 2020). "Knockdown of PAX8 in ovarian cancer cells with amplification or overexpression of this gene resulted in reduced viability, but not in cell lines without any alterations of this gene." (PMID 33488950, 2020). "This study aimed at investigating the immunohistochemical expression of PAX-8 among Sudanese females diagnosed with cervical, endometrial, and ovarian carcinomas." (PMID 32847623, 2020). "This study showed that the most expressed genes in ovarian carcinomas were PAX8 (paired box gene 8), EFNB1 (ephrin-B1) and mesothelin." (PMID 33121141, 2020). "In a recent study, HDAC inhibitors were reported to be effective in killing ovarian cancer cells and reducing tumor growth by suppressing oncogene PAX8 expression in a mouse model." (PMID 32698955, 2020). "Recent studies also showed that inhibition of histone deacetylases (HDACs) effectively suppressed ovarian cancer growth and metastasis by inhibiting expression of PAX8, a critical oncogene in ovarian cancer." (PMID 32698955, 2020). "The positive rate of PAX-8 in serous ovarian carcinoma is as high as 79%, which is one of the reliable indicators to differentiate primary ovary cancer from breast cancer." (PMID 32118786, 2020). "Here, we report that PAX8 is involved in migration and adhesion of both Fallopian tube secretory epithelial cells and ovarian cancer cells; in addition, it confers resistance to anoikis or detachment-induced apoptosis leading to EMT." (PMID 31832016, 2019). "Taken together, our comprehensive analyses identified a previously unrecognized lineage-specific PAX8 regulon in epithelial ovarian cancer." (PMID 31050342, 2019). "To complement the siRNA-based assays, we genetically knocked out PAX8 in four ovarian cancer cell lines (KURAMOCHI, HEY, SKOV3 and OVTOKO) by employing CRISPR-Cas9 technology with two independent single guide RNA (sgRNA) sequences." (PMID 31050342, 2019). "We concluded that PAX8 promoted ovarian cancer cell migration, at least partially, through activating the autocrine FGF18-FGFR signaling pathway." (PMID 31050342, 2019). "Taken together, targeting PAX8 or HDAC allowed for efficacious interventions of ovarian cancer growth and invasiveness in mice." (PMID 31050342, 2019). "Inhibition of PAX8 gene expression reduces the ability of ovarian cancer cells to migrate and adhere to the ECM and specifically to fibronectin and/or collagen substrates." (PMID 31832016, 2019). "Since our goal was to understand how the PAX8-ITGB3 interaction was organized in ovarian carcinoma, we performed network analysis before and after PAX8 silencing in SKOV3, extrapolating it from the general network." (PMID 31832016, 2019). "As suggested by recent studies, it is possible that new targets become available for PAX8 in ovarian cancer due to the reprogramming of PAX8 cistrome by epigenetic modifications that occur during tumorigenesis." (PMID 31832016, 2019). "We show that PAX8 plays a critical role in migration and adhesion of both Fallopian tube secretory epithelial cells and ovarian cancer cells." (PMID 31832016, 2019).
ovarian carcinoma (continued). "In recent years, the pro-tumorigenic role of PAX8 in ovarian cancer has been well demonstrated and PAX8 signaling network is under investigation to better tackle HGSC." (PMID 31832016, 2019). "To validate our observations, we assembled a patient-derived xenograft (PDX) cohort containing 221 models from seven different types of solid cancers, and RNAseq indicated that PAX8 was restrictedly expressed in two PDXs of epithelial ovarian cancer." (PMID 31050342, 2019). "PAX8 depleted Fallopian tube secretory cells and ovarian cancer cells were generated using short interfering siRNA." (PMID 31832016, 2019). "Our initial identification of an operative PAX8 regulon in ovarian carcinoma links lineage dependency with epigenetic vulnerability to HDAC inhibition." (PMID 31050342, 2019). "Increased expression of PAX8 was observed in ovarian cancer, bladder, prostate and endometrial carcinomas, however, its reduced expression was found in thyroid organogenesis." (PMID 29632436, 2018). "Pathologists have used PAX8 for decades as a histologic marker to define HGSC, but a genome-wide RNA interference screen of cancer cell lines was the first to identify the importance of PAX8 in ovarian cancer." (PMID 30096791, 2018). "Co-expression of WT-1 and PAX-8 was identified in six patients in P-CUP with presumed primary ovarian cancer." (PMID 29433539, 2018). "Studying PAX2 and PAX8 in this context provides valuable insight into the site of origin of ovarian cancer and the tumorigenic properties that make the PAX proteins promising drug targets for treatment of HGSC." (PMID 30096791, 2018). "PAX8 knockdown reduced proliferation, migration and invasion and increased apoptosis in ovarian cancer cells." (PMID 30096791, 2018). "PAX8 is required for the aggressive phenotype of ovarian cancer cells, as evidenced by the finding that silencing of Pax8 significantly decreased cell proliferation, migration, and invasion." (PMID 30021604, 2018). "PAX8 was the top-ranked differentially expressed gene in the screen between ovarian and non-ovarian cancer cell lines." (PMID 30096791, 2018). "Cytokeratin 7 (CK7) and paired box gene 8 (PAX8) are currently the best markers for determining primary origin in ovarian carcinoma, stomach cancer, and pancreatobiliary tract cancer." (PMID 30024911, 2018). "In appropriate clinical context, the prostate-specific antigen (PSA) for prostate cancer, PAX8 for ovarian cancer, alphafetoprotein for liver cancer, and TTF1 for lung cancer can be reliably used as a single marker." (PMID 29116378, 2018). "As a result, cells within an ovarian cyst have a higher likelihood of transforming into tubal-like cells that express markers of ovarian cancer, including PAX8, CA-125 and E-cadherin." (PMID 30096791, 2018). "PAX8 is a lineage-restricted transcription factor that is expressed in epithelial ovarian cancer (EOC) precursor tissues, and in the major EOC histotypes." (PMID 29312534, 2017). "The role of PAX8 in the functioning of the kidney and thyroid is established; but more recently this TF been recognized as a key driver in the development of epithelial ovarian cancer (EOC)." (PMID 29312534, 2017). "In conclusion, PAX8 is involved in transformed behavior of epithelial ovarian cancer cells in vitro, and suppresses tumor growth in vivo." (PMID 29312534, 2017). "PAX8 knockdown in ovarian cancer cell lines reduces in vitro and in vivo tumorigenicity and induces apoptosis." (PMID 29312534, 2017). "Our final suggestion is that the relevance of PAX8 in ovarian carcinoma lies in the downstream network(s) regulated by this transcription factor that contribute to ovarian carcinoma pathogenesis." (PMID 27259239, 2016). "On the basis of such evidences, it is conceivable that PAX8 is intimately involved in the progression of ovarian carcinomas." (PMID 27259239, 2016). "We have recently reported that PAX8 is involved in the tumorigenic phenotype of ovarian cancer cells." (PMID 27259239, 2016).
ovarian carcinoma (continued). "On the basis of our previous data and in order to clarify PAX8 contribution to ovarian cancer through the identification of its downstream gene regulatory network, we have transiently knocked-down PAX8 expression in both FT194 and SKOV-3 cells." (PMID 27259239, 2016). "In particular, we showed that PAX8 plays a critical role in the migration, invasion and tumorigenic ability of ovarian cancer cells." (PMID 27259239, 2016). "These pathological lesions expressed bonafide markers of ovarian cancer precursor lesions, Pax8 and Stathmin 1, and were presented with elevated mTOR signalling." (PMID 27036037, 2016). "In the present study, we intend to clarify PAX8 contribution to ovarian cancer through the identification of its downstream gene regulatory network." (PMID 27259239, 2016). "Both the primary and metastatic tumors stained positive for PAX8, a marker for embryonic Müllerian ducts, human fallopian tubes, and serous subtype of ovarian carcinomas." (PMID 27602775, 2016). "To evaluate if these epithelial lesions represent the precancerous state of ovarian cancer, we performed immunohistochemical localization of Pax8 and Stathmin 1, well-established markers of ovarian cancer precursor lesions and malignant disease." (PMID 27036037, 2016). "In the scenario of ovarian cancer, PAX8 is the currently available most important marker being a useful IHC target for the diagnosis of Mullerian tumors." (PMID 27259239, 2016). "The ovarian epithelial inclusion cysts in Hoxa5−/− mice also express the ovarian cancer markers PAX8 and WT1 suggesting that they constitute preneoplastic lesions and that the loss of Hoxa5 function confers ovarian cancer predisposition." (PMID 29615582, 2016). "This study explored the role of PAX8 in ovarian cancer progression by manipulating PAX8 expression and characterizing its effects in the fallopian tube, ovary, and HGSC cell lines." (PMID 27129161, 2016). "An ultrasound guided biopsy showed metastasis from ovarian cancer corresponding to a PAX8 overexpression on the histological examination." (PMID 25566350, 2014). "Our results show that RNA interference-mediated knockdown of PAX8 expression in SKOV-3 ovarian cancer cells produces a significant reduction of cell proliferation, migration ability and invasion activity compared with control parental SKOV-3 cells." (PMID 24766781, 2014). "To investigate the importance of PAX8 in the tumorigenicity of ovarian cancer cells in vitro and in vivo, we performed soft agar and nude mice assays." (PMID 24766781, 2014). "Overall, our results indicate that PAX8 plays an important role in the tumorigenic phenotype of ovarian cancer cells and identifies PAX8 as a potential new target for the treatment of ovarian cancer." (PMID 24766781, 2014). "Here, we show that PAX8 plays a critical role in the migration, invasion and tumorigenic ability of ovarian cancer cells." (PMID 24766781, 2014). "Our studies provide strong evidence that PAX8 plays an important role in the tumorigenicity of ovarian cancer cells both in vitro and in vivo and identify PAX8 as a major biomarker and target for ovarian cancer." (PMID 24766781, 2014). "In particular, PAX8 has been recently reported to be conspicuously expressed in human ovarian cancer, but the functional role of PAX8 in the carcinogenesis of this type of tumor has not been addressed." (PMID 24766781, 2014). "We first examined the expression of PAX8 in several ovarian cancer cell lines by RT-PCR and immunoblotting." (PMID 24766781, 2014). "To investigate the role of PAX8 in the tumorigenic properties of ovarian cancer cells, we silenced PAX8 expression in the SKOV-3 cell line using shRNA plasmid vectors." (PMID 24766781, 2014). "All together, these results indicate that PAX8 is involved in cell migration and invasion capabilities of ovarian cancer cells." (PMID 24766781, 2014). "Stable PAX8 depleted ovarian cancer cells were generated using short hairpin RNA (shRNA) constructs." (PMID 24766781, 2014).
ovarian carcinoma (continued). "The STOSE model is the first spontaneous HGSC model, as confirmed by the expression of immunohistochemical markers (pan-CK+, WT1+, inhibin−, PAX8+), consistent with human ovarian carcinomas." (PMID 24672774, 2014). "Using the prediction analysis of microarrays (PAM) method, the expression of 61 genes was analyzed in 68 breast and 57 ovarian carcinoma samples and PAX8 expression was found at higher levels in ovarian compared with breast cancer." (PMID 23425942, 2013). "Even among the 20 cases with uncertain primary organ sites based on cytology diagnosis, 13 samples with PAX8+/Calretinin- were confirmed with ovarian cancer both immunohistochemically and clinicopathologically." (PMID 23958394, 2013). "The application of PAX8 staining in appropriate clinical setting will be very useful for those patients presenting as advanced ovarian cancer prior to receiving neoadjuvant chemotherapy." (PMID 23958394, 2013). "When combining with Calretinin, PAX8 is a sensitive marker to diagnose the carcinomas of ovarian origin, which will be ideal to be used for those patients with a possible advanced ovarian cancer prior to receiving neoadjuvant chemotherapy." (PMID 23958394, 2013). "In the present study, we examined the utility of PAX8 antibody combining with Calretinin in differential diagnosis of cancer cells within the ascites from patients with advanced “ovarian” cancer." (PMID 23958394, 2013). "A genome-wide screen of pooled shRNAs in 25 ovarian cancer cell lines identified the transcription factor PAX8 (paired box gene 8), which is amplified in primary high grade ovarian tumors, as essential for survival and proliferation." (PMID 23528888, 2013). "For example, a study on ovarian cancer using CRISPR-Cas9 screening showed that deletion of the transcription factor PAX8 significantly enhanced the pro-ferroptosis effect of the GPX4 inhibitor RSL3, revealing PAX8 as a novel regulator of GPX4-dependent ferroptosis resistance in tumor cells." (PMID 40559667, 2025). "Notably, PAX8 is recognized as the prototypical lineage survival oncogene in epithelial ovarian cancer, and dysregulation of PAX8 promotes the progression of ovarian cancer." (PMID 38928435, 2024). "PAX8 was found to promote angiogenesis in ovarian cancer by interacting with SOX17, but whether it is related to angiogenesis in RCC remains unclear." (PMID 38928435, 2024). "PAX8 can be used to distinguish primary ovarian cancer from metastatic cancer." (PMID 38012622, 2023). "The ovarian cancer cell marker PAX8 remained present after long-term culture." (PMID 37853495, 2023). "Paired box 8 (PAX8) is a prototype lineage survival oncogene in epithelial ovarian cancer." (PMID 37894746, 2023). "Additionally, PAX8 can serve as a useful tool in distinguishing primary ovarian cancer from metastatic cancer." (PMID 38012622, 2023). "PAX8 has a role in transforming the ovarian cancer cell into mesenchymal phenotype." (PMID 35810383, 2022). "In vivo results showed that Curcumol inhibited the growth of ovarian cancer transplanted from nude mice and had synergistic effect with Niraparib, which may be related to the down-regulation of PAX8 expression." (PMID 35548853, 2022). "Meanwhile, the effect of PAX8 on ovarian cancer cells was analyzed by cell assay." (PMID 35548853, 2022). "In this study, Curcumol inhibited PAX8 expression in ovarian cancer cells." (PMID 35548853, 2022). "Our study showed that in comparison with the normal culture medium, the ADSC CM‐supplemented medium could significantly increase PAX8 levels in ovarian cancer cells." (PMID 33830648, 2021). "Moreover, because of its high expression in primary ovarian cancers, PAX8 is being considered as a target for ovarian cancer treatment as well." (PMID 34540435, 2021). "However, it was found that PAX8 gene expression was clearly detected in ovarian epithelial cancer cells." (PMID 34540435, 2021).